RN7SL192P (RNA, 7SL, cytoplasmic 192, pseudogene)
Gene: Miscellaneous RNA gene on chromosome 19 (11,011,708 to 11,012,006, forward strand). Ensembl gene ENSG00000276757.
Homologues: Orthologues: chimpanzee Metazoa_SRP (99% identical), macaque Metazoa_SRP (94% identical). Paralogues in human: RN7SL2 (82% identical), RN7SL1 (81% identical), RN7SL3 (79% identical), RN7SL45P (79% identical), RN7SL7P (79% identical), RN7SL408P (78% identical), RN7SL748P (78% identical), RN7SL709P (78% identical), Metazoa_SRP (77% identical), RN7SL230P (77% identical), RN7SL627P (77% identical), RN7SL113P (77% identical), and 701 more.